EGFR (epidermal growth factor receptor)
Diseases named in the same sentence as EGFR in open-access papers (continued):
Sharing a sentence is not in itself a finding about the gene and the disease.
lung adenocarcinoma (continued). "In addition, the co-existence of EGFR mutations and other genetic polymorphism that influence the prognosis of lung adenocarcinoma is not uncommon; the co-existence of EGFR mutation and endothelial nitric oxide synthase would significantly aggravate the lymph node invasion of lung adenocarcinoma." (PMID 32365566, 2020). "The low incidence of locoregional recurrence after complete resection reflects the distinctive nature of EGFR-mutant III-pN2 lung adenocarcinoma." (PMID 32922551, 2020). "Our case report provides clinical evidence of the durable response of a patient with advanced EGFR‐mutant lung adenocarcinoma to a combination of immunotherapy and anti‐angiogenic agent, sintilimab and bevacizumab, as subsequent‐line therapy." (PMID 32656988, 2020). "The present case indicated the potential benefit of anlotinib monotherapy in chemotherapy-refractory lung adenocarcinoma harboring wild-type EGFR status." (PMID 33031343, 2020). "Here, we demonstrate the first report of dual EGFR and ABL TKI treatment in a patient with concomitant EGFR-mutated lung adenocarcinoma and BCR-ABL1-positive chronic myeloid leukemia (CML)." (PMID 32257476, 2020). "In this study, we retrospectively analyzed the data from 103 stage IIIb–IV lung adenocarcinoma patients treated with EGFR TKIs at the Shandong Cancer Hospital between January 2014 and November 2017." (PMID 33585221, 2020). "A total of 277 patients with lung adenocarcinoma, divided into those harboring wild-type EGFR (n = 108, 40%) and those harboring mutant-type EGFR (n = 169, 60%) were included in this study." (PMID 32781755, 2020). "In contrast to the excellent activity of TKIs in mutant lung adenocarcinoma, TKIs showed a limited response in the PLELC patients with EGFR/ALK mutation in this study." (PMID 31794146, 2020). "Our previous study showed that concomitant EGFR mutation and ALK-rearrangement in synchronous multifocal lung adenocarcinomas was more frequent." (PMID 32375829, 2020). "In EGFR‐driven lung adenocarcinomas, EGFR pathway activation limited antitumor immunity by upregulating expression of PD‐1, PD‐L1, and inflammatory cytokines, as well as down‐regulating CTLs, which drives immune escape." (PMID 33034149, 2020). "Here, we report a rare case in which osimertinib had a poor effect on EGFR exon 20 insertion-positive lung adenocarcinoma." (PMID 33080698, 2020). "Analysis of the lung adenocarcinoma patients with wild-type EGFR in the TCGA database also demonstrated a significant correlation between high expression levels of CHRNA5 mRNA and poor overall survival outcome of patients." (PMID 32957649, 2020). "In the whole study population, the presence of CA9 SNP rs2071676 AG + GG were significantly correlated with a lower tumor stage of lung adenocarcinoma in both the whole study population (p = 0.044) and the EGFR wild type individuals (p = 0.033)." (PMID 32365566, 2020). "Since gain-of-function EGFR mutations tend to be mutually exclusive with loss-of-function SPRED1 and NF1 mutations in lung adenocarcinoma, we used oncogenic EGFR(L858R) as a model system." (PMID 32697994, 2020). "Further large cohort studies investigating the effect of CA9 SNP and EGFR phenotypes on the long-term survival rate of lung adenocarcinoma is mandatory." (PMID 32365566, 2020). "This study aimed to evaluate the association between prior EGFR-TKI therapy and incidence of acquired T790M resistance in lung adenocarcinoma patients who have progressed on first/second-generation EGFR-TKI therapy." (PMID 33014788, 2020). "Active mutation in the epidermal growth factor receptor (EGFR) kinase domain has been well studied and is known to be the main oncogenic-driven mutation in lung adenocarcinoma." (PMID 32092879, 2020). "The EGFR gene mutation and ALK-EML4 rearrangement in the lung adenocarcinoma and squamous cell carcinoma encouraged us to explore the tumor origin, and both tumors presented as treatment-naïve mutants occurring synchronously." (PMID 32727606, 2020).
lung adenocarcinoma (continued). "According to this finding, another group has shown that the increase in YAP expression leads to EGFR TKI resistance in lung adenocarcinomas." (PMID 33014812, 2020). "Accordingly, EGFR testing in mandatory at diagnosis for every patient with lung adenocarcinoma and for light smokers with squamous cell carcinoma (SCC), as well as for patients with progressive disease (PD) to TKIs." (PMID 32998450, 2020). "Somatic mutations in EGFR and KRAS as well as chromosome rearrangements affecting ALK, ROS1, and RET have been identified in human lung adenocarcinoma (LUAD)." (PMID 33348616, 2020). "Recently, it was reported that upregulated miR-147b in EGFR mutant lung adenocarcinoma cells mediates drug tolerance to EGFR TKI osimertinib via repression of Von Hippel-Lindau (VHL) and succinate dehydrogenase (SDH)." (PMID 32316322, 2020). "We conducted a retrospective study of patients with advanced lung adenocarcinoma treated with EGFR-TKI who showed a mental disorder or conscious disturbance." (PMID 32256269, 2020). "For instance, in human CL1-5 cells of lung adenocarcinoma, fucosylation, and sialylation of EGFR attenuates its activity." (PMID 33238647, 2020). "On other hand, alteration on the Epidermal Growth Factor Receptor (EGFR) gene is found in 15% of lung adenocarcinoma and translocations of the Anaplastic Lymphoma Kinase (ALK) gene occur in 3%-7% of lung adenocarcinoma." (PMID 32111002, 2020). "Our case reports an advanced EGFR‐mutant lung adenocarcinoma patient achieved PR and a PFS of 6 months to a combination of immunotherapy and anti‐angiogenic agent, sintilimab and bevacizumab, as subsequent‐line therapy." (PMID 32656988, 2020). "In lung adenocarcinoma with EGFR positivity, E19 dels predicts a good prognosis, while an E21 mutation is expected to increase mortality." (PMID 32053675, 2020). "Our latest study has showed that concomitant EGFR mutation and EML4-ALK rearrangement in lung adenocarcinoma was more frequent in multifocal lesions." (PMID 32375829, 2020). "In conclusion, the parallel biological effects of systemic EGFR pathway inhibition is observed in both tumor response and skin biopsies in patients with advanced lung adenocarcinoma." (PMID 33015988, 2020). "In the subgroup analysis of the male population, the presence of CA9 SNP rs2071676 AG + GG was also correlated with an earlier tumor stage (p = 0.037) and less possibility of lymph node invasion (p = 0.003) of lung adenocarcinoma in those with EGFR wild type." (PMID 32365566, 2020). "For example, preclinical findings have identified that inhibition of the interleukin-6 (IL-6)/STAT3 pathway can also inhibit tumor growth with EGFR mutation in NSCLC and suppress KRAS-driven lung adenocarcinoma." (PMID 33537237, 2020). "A prospective study also explored the impact of PIK3CA mutations on the clinical characteristics and treatment response to EGFR-TKIs in lung adenocarcinoma." (PMID 33363040, 2020). "We selected the EGFR exon 19 region and EGFR mutation for the evaluation of DNA, and thyroid transcription factor-1 (TTF-1) mRNA, which is one of the markers of lung adenocarcinoma." (PMID 32033355, 2020). "Earlier, our research group established and characterized an in vivo mouse NSCLC tumor model system, with wild type KRAS and EGFR genes, mimicking the majority of human lung adenocarcinomas." (PMID 30734151, 2020). "The coefficient of correlation (R2) of PD-L1 and c-MET expression in lung adenocarcinoma or the EGFR mutant subgroup was 0.332–0.387 (p < 0.05)." (PMID 31747941, 2019). "In clinical practice, platinum in combination with pemetrexed is the treatment of choice for patients with EGFR wild-type lung adenocarcinoma, whereas platinum combined with gemcitabine is the drug of choice for patients with lung SCC." (PMID 31319622, 2019). "Kirsten rat sarcoma viral oncogene homolog (KRAS) and epidermal growth factor receptor (EGFR) are the two most frequent and well-known oncogene of lung adenocarcinoma." (PMID 31783917, 2019).
lung adenocarcinoma (continued). "We consecutively collected 75 peripheral blood samples from patients diagnosed as having EGFR-mutant lung adenocarcinoma who were administered gefitinib or erlotinib as the first-line treatment." (PMID 30609749, 2019). "Lung adenocarcinomas with EGFR Mut in exon 19 had a lower R-score* than ones with EGFR Mut in exon 21 in training dataset (−0.39 ± 1.35 vs. 0.27 ± 1.12, P = 0.000) and in validation dataset (−0.70 ± 1.25 vs. 0.23 ± 1.12, P = 0.000)." (PMID 31993370, 2019). "Univariate and multivariate analysis of various predictive factors for the EGFR status in lung adenocarcinoma." (PMID 31380265, 2019). "Following the identification of KRAS and BRAF mutations, EGFR mutations were discovered in patients with lung adenocarcinoma (ADC) and were associated with the response to EGFR inhibitors." (PMID 31526368, 2019). "The in vivo tumor-targeting effect of LXY30 was evaluated in a subcutaneous and intracranial mouse models generated from EGFR-mutant lung adenocarcinoma H3255 cells by optical imaging." (PMID 31182116, 2019). "For capmatinib targeting MET in EGFR mutated lung adenocarcinoma with disease progression on EGFR-TKI treatment, gains of ≥ 6 copies have been related to response to combined MET and EGFR targeting." (PMID 30888490, 2019). "Previous reports showing successful treatment of EGFR exon 20 insertion-positive lung adenocarcinoma with the standard osimertinib dose of 80 mg are limited." (PMID 31645848, 2019). "The results indicate that miR-145 is a cell proliferation suppressor in lung adenocarcinoma by targeting EGFR and NUDT1 as an ERK and AKT phosphorylation inhibitor, which enhances gefitinib cytotoxicity in NSCLC." (PMID 31619200, 2019). "For example, Methyltransferase-like 3 (METTL3), one of the m6A writers, is upregulated in lung adenocarcinoma and play oncogenic effect by promoting translation of its target mRNA transcripts including EGFR and TAZ63." (PMID 31653849, 2019). "Here, we screened 230 Chinese patient samples of lung SCC and reported the rarity of two most ubiquitous mutations in KRAS and EGFR seen in lung adenocarcinoma, while PIK3CA mutations were relatively high when compared with lung adenocarcinoma." (PMID 31749831, 2019). "We used RNA-seq to screen gene expression levels in local advanced lung adenocarcinoma patients who received EGFR-TKI (gefitinib or ecotinib) therapy." (PMID 31801598, 2019). "The mutational frequency of EGFR and KRAS genes in lung adenocarcinoma varies worldwide per ethnicity and smoking." (PMID 30824880, 2019). "SP-D has recently been shown to inhibit the proliferation, migration and invasion of A549 human lung adenocarcinoma cells by binding to N-glycans of epidermal growth factor receptor (EGFR) via its CRD region, and interfering with EGF signaling." (PMID 31355132, 2019). "Recently, aldehyde dehydrogenase 1 (ALDH1) induction has been found to render lung adenocarcinomas resistant to EGFR-TKIs, and targeting ALDH1A1 becomes a novel strategy to overcome resistance." (PMID 31695757, 2019). "The use of any first- or second-generation EGFR-TKIs alone for the treatment of intracranial involvement in patients with EGFR mutant-positive lung adenocarcinoma showed a favorable cerebral response rate of more than 50%9,10." (PMID 31728013, 2019). "This incidence was higher than the prevalence of ALK and concomitant ALK and EGFR alterations in multifocal lung adenocarcinomas." (PMID 31861060, 2019). "We demonstrated that patients’ PS rapidly improved after shunt surgery and they recovered to a state matching the indication criteria for EGFR-TKI administration for lung adenocarcinoma." (PMID 30629621, 2019). "Recently, it has been reported that the use of Akt inhibitor plus EGFR-TKIs led to suppressed growth in lung adenocarcinoma models of TKI resistance." (PMID 31801598, 2019).
lung adenocarcinoma (continued). "Patients with surgically resected lung adenocarcinoma (n = 72) were enrolled, including 12 patients with KRAS mutations and 60 patients with EGFR mutations." (PMID 31783917, 2019). "The prevalence was consistent with our findings where distinct types of genetic alterations in EGFR were detected in 7 out of 20 patients (35%) diagnosed with lung adenocarcinoma who were younger than 36 years." (PMID 30821106, 2019). "Of the 697 patients with lung adenocarcinoma, 224 patients were in stage IV and had results on both TTF-1 IHC and EGFR mutations." (PMID 31196060, 2019). "To date, few reports have been published on the use of Apatinib Mesylate against EGFR-TKI resistance in lung adenocarcinoma patients." (PMID 31570733, 2019). "The treatment strategy for brain metastasis (BM) in patients with epidermal growth factor receptor (EGFR) -mutant lung adenocarcinoma (LAC) remains controversial." (PMID 31399067, 2019). "Third, histologic or phenotypic transformation of the lung adenocarcinoma subtype to small cell carcinoma has been observed in 3–15% of patients with clinically demonstrated acquired resistance to EGFR-TKIs, including third-generation TKIs." (PMID 31815659, 2019). "For lung adenocarcinoma, alterations in EGFR, KRAS, and BRAF were comparable between protocol patients and TCGA (data not shown)." (PMID 32914008, 2019). "The purpose of this study is to compare the characteristics measured with dual-energy spectral computed tomography (DESCT) in lung adenocarcinoma patients who have KRAS and EGFR gene mutations." (PMID 31783917, 2019). "Functional studies have demonstrated proliferative potential of FAM83H‐AS1 through MET/EGFR signaling in lung adenocarcinoma and NOTCH1 signaling pathway in colorectal cancer." (PMID 30959550, 2019). "Similar to Western population, the two most ubiquitous mutations were those in EGFR and KRAS in the case of lung adenocarcinoma samples." (PMID 31749831, 2019). "Most lung adenocarcinomas harbor mutations in KRAS gene (32%) and epidermal growth factor receptor (EGFR) (11%), resulting in overactivation of the RAS-RAF-MEK-ERK pathway." (PMID 31027181, 2019). "Genetic alterations of the epidermal growth factor receptor (EGFR) occur in approximately 20% of patients with lung adenocarcinomas in Western countries and 40–60% in East Asia for." (PMID 30760227, 2019). "To understand the association of GK5 expression and EGFR TKI resistance, we collected EDTA plasma samples from 28 lung adenocarcinoma patients, of which 17 and 11 were sensitive and resistant to EGFR-TKIs, respectively." (PMID 30791926, 2019). "The results indicated that AM had a better impact on lung adenocarcinoma patients who underwent EGFR-TKIs treatment while the disease still progressed." (PMID 31570733, 2019). "This study developed a deep supervised learning approach to predict EGFR‐mutant lung adenocarcinoma in CT images." (PMID 31074592, 2019). "DEPTOR presented low expression in tumor samples compared to adjacent non-tumor samples and was found to inhibit tumor cell proliferation in vitro and in vivo by promoting EGFR degradation in lung adenocarcinoma." (PMID 31228948, 2019). "Cellular polymorphism is remarkable in EGFR wild type NCI-H1568 cells, which is a cell line derived from lymph node metastasis of lung adenocarcinoma." (PMID 31069016, 2019). "The PC9 cell line is derived from the lung adenocarcinoma cells of a gefitinib-sensitive patient harboring a five-amino-acid deletion in the EGFR tyrosine kinase domain in cancer tissues." (PMID 30532069, 2019). "Herein, we reported the association of EGFR and KRAS mutational status with clinicopathological features from approximately 500 Brazilian lung adenocarcinoma patients attended at the Barretos Cancer Hospital." (PMID 30824880, 2019). "To confirm the change in IGFBP7 after acquired resistance to EGFR-TKIs, we collected 24 malignant pleural effusions of EGFR-mutant lung adenocarcinoma for IGFBP7 mRNA analysis." (PMID 30609749, 2019).
lung adenocarcinoma (continued). "Recently, aldehyde dehydrogenase 1 (ALDH1) induction has been found to render lung adenocarcinomas resistant to EGFR-TKIs, and targeting ALDH1 has emerged as a novel strategy for treating lung cancer 2-4." (PMID 31695757, 2019). "Firstly, negligible amounts of patients with lung adenocarcinoma were included in the ALTER0303 trial, of which 138 (31.6%) patients had EGFR sensitive mutation, and 133 (96%) received prior EGFR TKI and at least two lines of systemic chemotherapy." (PMID 31221221, 2019). "Our data adds confirmation with earlier work that lung squamous cell carcinoma shows a rare presence of two ubiquitous mutations seen in lung adenocarcinomas, KRAS and EGFR, are rare in lung squamous cell carcinoma." (PMID 31749831, 2019). "Lung adenocarcinomas driven and maintained by mutant activating epidermal growth factor receptor (EGFR) respond remarkably to EGFR-tyrosine kinase inhibitors (TKIs) such as erlotinib." (PMID 31695757, 2019). "EGFR-Mut lung adenocarcinomas had a lower R-score than EGFR-WT ones in training dataset (−0.40 ± 0.50 vs. 0.05 ± 0.68, P = 0.000), which was confirmed in validation dataset (−0.37 ± 0.51 vs. 0.01 ± 0.0.58, P = 0.000)." (PMID 31993370, 2019). "The mutation of epidermal growth factor receptor (EGFR), which is the first discovered and prototypical member of receptor tyrosine kinase family (RTK), is markedly prevalent (40–60%) in lung adenocarcinoma." (PMID 31570733, 2019). "ROR1 is also required to sustain the association between EGFR and receptor tyrosine-protein kinase erbB-3 (ERBB3), the activation of ERBB3, consequentially, making ROR1 an ideal target for therapies against EGFR-TKI resistance in lung adenocarcinoma." (PMID 31452776, 2019). "Concluding, this is the largest study assessing EGFR and KRAS mutation status in the Brazilian lung adenocarcinoma population." (PMID 30824880, 2019). "HGF not only activates the c-MET signaling pathway to induce EGFR-TKIs resistance in lung adenocarcinomas, but it also promotes the transcription of the endogenous c-MET gene." (PMID 31747941, 2019). "This is because KRAS mutations are detected in 25% of lung adenocarcinomas, which are associated with reduced survival in NSCLC patients, as well as resistance to EGFR TKIs." (PMID 31428570, 2019). "In lung adenocarcinoma, recent studies have confirmed that AXL inhibition decreased the expression of PD-L1 and CXC chemokine receptor 6 (CXCR6), especially when EGFR was mutated." (PMID 31703465, 2019). "Examples include epidermal growth factor receptor (EGFR) inhibitors, such as erlotinib in advanced lung adenocarcinoma, and cetuximab and panitumumab in metastatic colorectal cancers." (PMID 31546879, 2019). "In conclusion, we assessed the clinicopathological and ethnic impact of EGFR and KRAS mutations in the largest series reported of Brazilian lung adenocarcinomas." (PMID 30824880, 2019). "Low EGFR expression was observed in lung adenocarcinomas compared to squamous cell lung carcinoma, especially if simultaneously MIG6 expression was high." (PMID 31069016, 2019). "Compared with previously documented factors such as good performance status, EGFR mutations, age, sex, smoking status, and distant metastasis, TTF-1 positivity has the most significant prognostic impact in advanced lung adenocarcinoma." (PMID 31196060, 2019). "In the subgroup analysis of lung adenocarcinomas tested for EGFR, the female-to-male hazard ratio remained unaltered in the models adjusted for sex differences in EGFR mutational status." (PMID 31247015, 2019). "In human lung adenocarcinomas, MIG6 was associated with EGFR-TKI resistance of putative dormant cancer cells and epithelial mesenchymal transition (EMT) induced refractoriness." (PMID 31069016, 2019). "From the 51 patients, 40 patients with stage IV lung adenocarcinoma treated with an EGFR TKI as their first-line therapy were enrolled in the following outcome analysis." (PMID 31652678, 2019).